SOX9 (SRY-box transcription factor 9)
Diseases named in the same sentence as SOX9 in open-access papers (continued):
Sharing a sentence is not in itself a finding about the gene and the disease.
Arthritis (5 papers, 2008 to 2024). Inflammation of a joint. "The interesting reversal of sex susceptibility to arthritis and the observations that congenic males show impaired development of genital organs and that females are more aggressive and less caring mothers have made us pay attention to the Sox9 gene." (PMID 18684326, 2008). "Activation of Sox9 by p38-MAP kinase signaling results in chondrocyte growth and differentiation while depression of Sox9 transcription results in cartilage degeneration and osteo-arthritis." (PMID 23637819, 2013).
gastric adenocarcinoma (5 papers, 2019 to 2026). "SOX9 expression was analyzed by immunohistochemistry in 333 gastric adenocarcinoma cases, and its association with clinicopathological and follow-up data was evaluated." (PMID 31275454, 2019). "Our study aimed to explore the relationship between SOX9 expression and pathological data in gastric adenocarcinoma and to evaluate its potential as a prognostic immunohistochemical marker." (PMID 39907598, 2025). "This study aimed to evaluate the relationship between SOX9 immunohistochemistry results and the pathological and clinical characteristics of gastric adenocarcinoma, assessing its potential as a prognostic marker." (PMID 39907598, 2025). "The primary objective of this study was to elucidate the relationship between SOX9 expression and the pathological and clinical characteristics of gastric adenocarcinomas, as well as its predictive significance in the progression and prognosis of GC." (PMID 39907598, 2025). "Epithelial SOX9 drives gastric adenocarcinoma progression and metastasis by inducing M2 macrophage repolarization through the paracrine leukaemia inhibitory factor (LIF) and suppressing CD8 + T-cell function." (PMID 40594780, 2025). "Further subgroup analysis suggested prognostic value of SOX9 expression in poorly differentiated gastric adenocarcinoma." (PMID 35221802, 2022). "Collectively, these findings align with the majority of the literature in suggesting that SOX9 may play a pivotal role in shaping the clinicopathological profile of gastric adenocarcinomas." (PMID 39907598, 2025). "Absence of SOX9 nuclear staining was found in 3 (2%) gastric adenocarcinoma patients." (PMID 39907598, 2025).
hypertrichosis (5 papers, 2012 to 2025). Excessive hair growth anywhere on the body. "Here, we establish that a position effect on the Trps1 target gene SOX9 is likely involved in the pathology of human hypertrichosis." (PMID 23133399, 2012). "Furthermore, we identify a copy number variation less than 1 Mb upstream of SOX9 in a family with CGHT that significantly decreases expression of the gene in the hair follicle, providing significant insight into the pathology of human hypertrichosis." (PMID 23133399, 2012).
Infertility (5 papers, 2009 to 2022). "SOX9 mutations identified in DSDs are often involved in human infertility caused by testis gonadal dysgenesis, or XY and XX sex reversal." (PMID 33810596, 2021). "Furthermore, abnormalities arising from mutations in the SOX9 regulatory or coding regions indicate the importance of functional SOX9 protein; craniofacial disorders, testicular dysgenesis and infertility can all arise from such mutations." (PMID 33810596, 2021). "Testicular samples from mice whose Sertoli-cells lack Sox9 from E14.0 onwards were isolated before the onset of infertility at the age of 90 days post partum (dpp) and at 165 dpp, when the phenotype was clearly detectable." (PMID 21182756, 2010). "Lower SOX9 expression indicated dysfunction of Sertoli cells, which may be responsible for infertility of mice in the HGE group." (PMID 32111017, 2020). "It is known that Sox9 inhibits Wnt signaling in chondrocytes and that abnormal activation of the Wnt pathway in mouse Sertoli cells leads to degeneration of tubules and infertility, a phenotype reminiscent of the one reported for AMH-Cre Sox9flox/flox mice." (PMID 21182756, 2010). "For example, three possible target genes for down-regulated miRNAs, TIMP3, SOX9 and GADD45G, were significantly increased in infertile testis." (PMID 19210773, 2009). "In a family with two 46, XX infertile males, both have a 96 kb triplication 500 kb upstream of SOX9 and present with hypotrophic testes containing no sperm." (PMID 33810596, 2021). "We speculate that perturbed Tcf7l2-dependent Wnt signaling might contribute to late-onset infertility in the absence of Sox9 in Sertoli cells." (PMID 21182756, 2010).
injury (5 papers, 2018 to 2024). Damage inflicted on the body as the direct or indirect result of an external force, with or without disruption of structural continuity. "Previous results have also shown that cells expressing transcription factor Sox9 were an important factor in the repair and regeneration of radiation-induced lung injury." (PMID 37175945, 2023). "In liver biopsies of acute liver injury patients, SOX9‐positive biphenotypic hepatocytes appeared in the liver parenchyma which is accompanied by elevation of plasma IL‐8 levels." (PMID 31651102, 2019). "In liver biopsies of acute liver injury patients, we observed the appearance of SOX9‐positive biphenotypic hepatocytes accompanied by elevation of plasma IL‐8 levels." (PMID 31651102, 2019). "Additionally, the Sox9 gene has been shown in other lung injury models, such as radiation-induced acute lung injury, to contribute to regeneration via the PI3K/AKT pathway, with lung epithelial cells exhibiting increased proliferation potential." (PMID 39346085, 2024). "Post-AKI, renal injury promoted Sox9 expression and stimulated the expansion of EGFP+ cells, but most descendants of EGFP+ cells no longer expressed Sox9." (PMID 34746706, 2021).
intrahepatic cholangiocarcinoma (5 papers, 2017 to 2025). A carcinoma that arises from the intrahepatic bile duct epithelium in any site of the intrahepatic biliary tree. "SOX9 contributes to the development of gemcitabine resistance in intrahepatic cholangiocarcinoma by inhibiting CHK1-mediated homologous recombination repair (HRR) activity." (PMID 40240356, 2025). "Additionally, nuclear localization of Sox9 in intrahepatic cholangiocarcinoma (ICC) correlated with moderately or poorly differentiated status, and Sox9 overexpression in ICC was associated with increased invasiveness and poorer prognosis." (PMID 30992706, 2019). "However, SOX9 function in intrahepatic cholangiocarcinoma (iCCA) is unknown." (PMID 30420613, 2018).
lung diseases (5 papers, 2015 to 2024). "The human SOX2+SOX9+ cells they cultured could potentially be used to model pediatric lung diseases (such as bronchopulmonary dysplasia), which are thought to originate during lung development." (PMID 28806170, 2017). "Indeed, because human SOX2+SOX9+ cells are derived from embryonic lungs, they are likely to more faithfully reflect the epigenetic features of the embryonic cells that contribute to pediatric lung disease than cells derived from adult lung epithelial cells or iPSCs." (PMID 28806170, 2017). "Notably, among these top expressed genes, genes such as SOX9 (SRY-Box Transcription Factor 9) and MMP11(Matrix Metallopeptidase 11) are involved in epithelial-mesenchymal transition (EMT) which is involved in many different lung diseases." (PMID 39026356, 2024).
metastatic melanoma (5 papers, 2013 to 2019). A melanoma that has spread from its primary site to another anatomic site. "These levels fall within the range of high SOX9 expression being detected in the metastatic melanoma samples (10 to 44-fold vs normal skin)." (PMID 30642390, 2019). "To address this issue, we first performed comparative expression study of these factors on tissue sections from Chinese patients with benign melanocytic nevus, primary dermal and metastatic melanomas using antibodies specific for SOX9, SOX10, and NEDD9." (PMID 30642390, 2019). "Only T1 and N0 stage in metastatic melanomas were significant between SOX9 high and low." (PMID 25885555, 2015). "We confirm that SOX9 expression is regulated by DNA methylation and has a role in cell cycle regulation, invasion in vitro and in vivo and could be a prognostic marker for overall survival in metastatic melanoma patients." (PMID 25885555, 2015). "Thus, SOX9 could potentially be a prognostic marker for metastatic melanoma." (PMID 25885555, 2015). "Indeed, SCD5 overexpression in metastatic melanoma was sufficient to reduce PRAME, in turn activating MITF and SOX9, which were further increased by ATRA." (PMID 29484133, 2018).
prostate tumor (5 papers, 2010 to 2020). "In these studies we have focused on assessing three genes: Hes6, Sox9 and Jmjd1a, which were implicated in prostate tumors, and were shown (by us and others) to be regulated by HIF." (PMID 21037926, 2010). "Based on our identification of novel proteins associated with the NE lesions and NE prostate tumors we assessed expression of Hes6 and Sox9 in tissue specimens." (PMID 21037926, 2010). "The expression of Nwd1is strikingly upregulated by Sox9, a transcription factor in malignant prostate tumor cells." (PMID 32344379, 2020). "Although the nearest protein-coding regions, KCNJ2 and SOX9, are ∼1Mb away, SOX9 is involved in prostate epithelial differentiation and observed to promote prostate tumor cell proliferation when upregulated." (PMID 23593118, 2013).
rectal cancer (5 papers, 2019 to 2025). A primary or metastatic malignant neoplasm that affects the rectum. "SOX9 overexpression is associated with increased mortality in many cancers, including colon and rectal cancers." (PMID 33428592, 2021). "Overexpression of SOX9 stimulates the Wnt/β‐catenin signaling pathway, and the SOX9‐Wnt/β‐catenin axis governs the development of human lung, gastric, and rectal cancers." (PMID 40626133, 2024). "To further investigate whether SOX9 gene expression is associated with survival outcomes in patients with CRC, we performed survival analyses using data from the TCGA Colon and Rectal Cancer (COADREAD) cohort." (PMID 40179020, 2025).
vitiligo (5 papers, 2010 to 2018). Generalized well circumscribed patches of leukoderma that are generally distributed over symmetric body locations and is due to autoimmune destruction of melanocytes. "Autoantibodies against TPH have been associated with alopecia, vitiligo, and enamel dysplasia and anti-SOX9/SOX10 antibodies with vitiligo." (PMID 27597936, 2016). "In addition, antibodies against SOX9/10 are increased in the sera of APECED patients with vitiligo but are rarely found in patients with isolated vitiligo." (PMID 31548517, 2017). "Notably, auto-antibodies against the transcription factors SOX9 and SOX10, important in the development of melanocytes, have been detected in APECED patients and are highly associated with skin symptoms such as vitiligo." (PMID 22506061, 2012). "The transcription factors SRY-box 9 (SOX9) and SRY-Box 10 (SOX10) were reported to be vitiligo autoantigens in APS-1 patients with autoantibodies detected in 15 and 22% of sera, respectively." (PMID 30002654, 2018). "Furthermore, SOX9 and SOX10 transcription factors are vitiligo autoantigens in APECED." (PMID 21197407, 2010).
bladder tumours (4 papers, 2008 to 2024). "In this new scenario, SOX9 represents a candidate target gene supporting the potential use of this type of drugs to achieve their demethylation and reactivation in bladder tumours." (PMID 18087279, 2008). "SOX9 methylation has been described in bladder tumours and in FL." (PMID 21603610, 2011). "In primary bladder tumours, SOX9 hypermethylation was present in 56.4% of the cases." (PMID 18087279, 2008). "Moreover, this independent set of 101 bladder tumours served to explore the clinical relevance of the identified methylation for SOX9." (PMID 18087279, 2008). "An independent set of 10 pairs of bladder tumours and normal urothelium, similar to the set used for the discovery of explorative analyses, was utilised to validate the presence of cancer-specific methylation of SOX9 by an independent method, MS-PCR." (PMID 18087279, 2008). "SOX9 methylation was found with rates higher than 70% in bladder tumours and lower than 20% in their normal urothelium counterparts, an observation suggesting that SOX9 could be methylated in a cancer-specific manner." (PMID 18087279, 2008). "Furthermore, SOX9 promoter hypermethylation was frequently found in bladder tumours." (PMID 18087279, 2008). "In the context of gemcitabine, the 5637GR bladder tumors had elevated expression of the OVOL1 target genes, including SOX2 and SOX9, in a OXCT1-dependent manner, resulting in greater mitotic index." (PMID 39509334, 2024).
bronchiectasis (4 papers, 2018 to 2022). Segmental, irreversible dilation of the bronchial tree resulting in the accumulation of secretions which leads to obstruction. "Transplantation of autologous SOX9+ BCs enhanced lung tissue repair and lung function in two patients with bronchiectasis." (PMID 35130980, 2022). "A trial of transplantation of Sox9+ cells (including basal-like cells) into injured lung claimed to be able to improve the recipients’ (bronchiectasis patients) lung function." (PMID 35130980, 2022). "To explore the clinical feasibility of autologous SOX9+ BC transplantation, we conducted a pilot trial aiming to treat bronchiectasis by regenerating functional human lung." (PMID 29344809, 2018). "We show here that supplement of expandable SOX9+ BCs by autologous transplantation could repair the damaged lung in two bronchiectasis patients in both pulmonary structure and function." (PMID 29344809, 2018). "Moreover, we conducted the first autologous SOX9+ BCs transplantation clinical trial in two bronchiectasis patients." (PMID 29344809, 2018). "Two patients diagnosed as non-CF bronchiectasis were firstly enrolled for autologous SOX9+ BC transplantation on April, 2016." (PMID 29344809, 2018). "Interestingly, the transplantation of autologous adult human SOX9+ airway BCs into bronchiectasis patients improved their lung function and no aberrant cell growth nor other related adverse events were observed during the whole follow-up period." (PMID 36010671, 2022).
cardiac hypertrophy (4 papers, 2021 to 2023). "In a murine model of cardiac hypertrophy, a pathology that involves fibrosis, Sox9, Tgfb2, and Tgfb3 were mutually upregulated and predicted to interact; however, this was not experimentally confirmed or linked to ECM regulation." (PMID 37510994, 2023). "Several recognized hypertrophic factors, including myc and sox9, which were upregulated in the dataset of the mouse myocardial hypertrophy model, were among the predicted TFs." (PMID 35964009, 2022). "For instance, a study demonstrated that SOX9 deletion in cardiomyocytes suppressed cardiac hypertrophy and fibrosis." (PMID 34531378, 2021).
cholestasis (4 papers, 2018 to 2025). Impairment of the bile flow caused by obstruction within the liver, or outside the liver in the bile duct system. "The mouse line successfully avoided the potential lesions caused by embryonic-stage Sox9 deletion such as the delayed maturation of bile ducts, cholestasis, and the high levels of serum bilirubin, and provided reference for studying the role of Sox9 in other organs." (PMID 37649095, 2023). "Opn+ hepatocytes appeared less abundant compared to Sox9 or Hes1 in all models, with the highest frequencies in cholestasis (BDL and DDC)." (PMID 41290681, 2025). "In our present study, p21 seemed to be activated in both SOX9-negative and SOX9-positive hepatocytes at the initial cholestatic progression stage in order to respond to cholestasis stress." (PMID 35313986, 2022). "The co-treatment of GCA and VP gradually reduced expression levels of Sox9 and the YAP target genes Cyr61, Ctgf, Afp and Ankrd1 indicating a direct link between cholestasis mediated expression of Sox9 through activation of YAP, which is independent of RBPJ." (PMID 30501048, 2018). "In addition, from our study of in vitro cholestatic liver injury, we could show that upregulation of Sox9 expression upon induction of cholestasis is independent of Notch signalling." (PMID 30501048, 2018).
chronic kidney disease (4 papers, 2020 to 2025). Impairment of the renal function secondary to chronic kidney damage persisting for three or more months. "Haixia Mao and colleagues found that serum levels of PIIINP, TGF-β1, and SOX9 were considerably elevated in a rat model of chronic kidney disease compared to the control group." (PMID 39974732, 2025). "Collectively, PGE2‐mediated activation of Sox9+ cells may play an important role in promoting functional recovery from kidney injury and inhibiting the transformation into chronic kidney disease by promoting the restoration of the structure and metabolism of the proximal tubules." (PMID 38801100, 2024). "Single-cell suspensions obtained from needle kidney biopsy tissue of patients with chronic kidney diseases (CKD) were seeded for cell culture, yielding clones consisting of proliferative (KI67+) cells that expressed SOX9 and PAX2." (PMID 39872058, 2023).
cleft palate (4 papers, 2014 to 2025). Cleft palate is a fissure type embryopathy that affects the soft and hard palate to varying degrees. "This loss of SOX9 was also associated with cleft palate in addition to skeletal malformations and sex reversal." (PMID 37840956, 2023). "SOX9 overexpression in chondrocytes is known to cause cleft palate in mouse." (PMID 33577554, 2021). "Topiramate treatment of primary MEPM cells also increased expression of SRY-Box Transcription Factor 9 (SOX9), a TGFB1 target that causes cleft palate when abnormally expressed." (PMID 33577554, 2021). "In the autosomal dominant families reported with these regulatory mutations affecting SOX9, PRS represents the most severe end of a spectrum that includes cleft palate with micrognathia and isolated micrognathia." (PMID 24363063, 2014). "Furthermore, both knockdown and overexpression of Sox9 in mouse has been shown to result in cleft palate phenotypes." (PMID 33577554, 2021). "Given the high concordance of cleft palate and micrognathia in the affected individuals, we hypothesized that SATB2 may be a target of the transcription factor SOX9 as CRMs affecting SOX9 are a significant cause of PRS." (PMID 24363063, 2014).
disorders of sex development (4 papers, 2011 to 2019). "Heterozygous loss-of-function mutations in human SOX9 cause sex development disorder in XY males while gain-of-function mutations, such as gene duplication, can lead to XX female DSD55." (PMID 31745224, 2019). "In a previous study, copy number variants of a long distance regulatory region named RevSex, located 517–595 kb upstream of SOX9, were discovered in human DSD (disorders of sex development) patients and seem to be associated with gonadal expression of SOX9." (PMID 25265165, 2014). "In human embryogenesis, loss of SRY (sex determining region on Y), SOX9 (SRY-related HMG box 9) or SF1 (steroidogenic factor 1) function causes disorders of sex development (DSD)." (PMID 21412441, 2011). "Here the authors by studying duplications and deletions upstream of SOX9 from patient samples with disorders of sex development (DSD) reveal enhancers for SOX9 critical for human sex development and DSD." (PMID 30552336, 2018).
dwarfism (4 papers, 2007 to 2018). "In mice, overexpression of Sox9 in osteoblasts from a 2.3-kb Col1a1 promoter resulted in dwarfism and osteopenia, with a significant reduction in bone volume, osteoblasts number and bone formation rate." (PMID 29176883, 2017).